UQCRFS1 (ubiquinol-cytochrome c reductase, Rieske iron-sulfur polypeptide 1)
Description:
[Cytochrome b-c1 complex subunit Rieske, mitochondrial]: Component of the ubiquinol-cytochrome c oxidoreductase, a multisubunit transmembrane complex that is part of the mitochondrial electron transport chain which drives oxidative phosphorylation. The respiratory chain contains 3 multisubunit complexes succinate dehydrogenase (complex II, CII), ubiquinol-cytochrome c oxidoreductase (cytochrome b-c1 complex, complex III, CIII) and cytochrome c oxidase (complex IV, CIV), that cooperate to transfer electrons derived from NADH and succinate to molecular oxygen, creating an electrochemical gradient over the inner membrane that drives transmembrane transport and the ATP synthase. The cytochrome b-c1 complex catalyzes electron transfer from ubiquinol to cytochrome c, linking this redox reaction to translocation of protons across the mitochondrial inner membrane, with protons being carried across the membrane as hydrogens on the quinol. In the process called Q cycle, 2 protons are consumed from the matrix, 4 protons are released into the intermembrane space and 2 electrons are passed to cytochrome c. The Rieske protein is a catalytic core subunit containing a [2Fe-2S] iron-sulfur cluster. It cycles between 2 conformational states during catalysis to transfer electrons from the quinol bound in the Q(0) site in cytochrome b to cytochrome c1 (By similarity). Incorporation of UQCRFS1 is the penultimate step in complex III assembly. [Cytochrome b-c1 complex subunit 9]: Component of the ubiquinol-cytochrome c oxidoreductase (cytochrome b-c1 complex, complex III, CIII). UQCRFS1 undergoes proteolytic processing once it is incorporated in the complex III dimer. One of the fragments, called subunit 9, corresponds to its mitochondrial targeting sequence (MTS). The proteolytic processing is necessary for the correct insertion of UQCRFS1 in the complex III dimer, but the persistence of UQCRFS1-derived fragments may prevent newly imported UQCRFS1 to be processed and assembled into complex III and is detrimental for the complex III structure and function.
Synonyms: RISP; ISP; RIS1; RIP1; UQCR5; MC3DN10
Tractability: Small molecule: a structure with a bound ligand is known. Antibody: UniProt predicts a signal peptide or a membrane-spanning region. PROTAC: ubiquitination databases record sites on it; its protein half-life has been measured.
Gene: Protein-coding gene on chromosome 19 (29,205,320 to 29,213,151, reverse strand). Ensembl gene ENSG00000169021.
Subcellular location: Mitochondrion inner membrane
Subcellular location (Human Protein Atlas): Mitochondria
Pathways (Reactome):
Metabolism: Complex III assembly; Respiratory electron transport
Gene Ontology:
Molecular function: protein binding; oxidoreductase activity; quinol-cytochrome-c reductase activity; 2 iron, 2 sulfur cluster binding
Biological process: mitochondrial respiratory chain complex III assembly; respiratory electron transport chain; mitochondrial electron transport, ubiquinol to cytochrome c; proton transmembrane transport
Cellular component: mitochondrion; respiratory chain complex III; mitochondrial inner membrane; mitochondrial matrix; membrane; mitochondrial membrane
Genetic constraint (gnomAD): Loss-of-function variants: 6 observed, 14.88 expected, observed/expected ratio (o/e) 0.4, 90% interval 0.22 to 0.8. The upper end of that interval is the gene's LOEUF score, 0.8, which puts it in group 3 of 6, group 1 being the genes least tolerant of losing a copy. Missense variants: 203 observed, 306.42 expected, observed/expected ratio (o/e) 0.66, 90% interval 0.59 to 0.74. Synonymous variants: 105 observed, 128.52 expected, observed/expected ratio (o/e) 0.82, 90% interval 0.7 to 0.96.
Gene-disease validity (ClinGen):
ClinGen rates the evidence that UQCRFS1 causes each of these diseases.
mitochondrial disease (autosomal recessive): Moderate.
Homologues: Orthologues: chimpanzee UQCRFS1 (99% identical), rat Uqcrfs1 (89% identical), guinea pig UQCRFS1 (89% identical), mouse Uqcrfs1 (89% identical), dog UQCRFS1 (88% identical), pig UQCRFS1 (82% identical), tropical clawed frog uqcrfs1 (77% identical), zebrafish uqcrfs1 (69% identical), Drosophila melanogaster RFeSP (52% identical), Caenorhabditis elegans isp-1 (47% identical).
Diseases named in the same sentence as UQCRFS1 in open-access papers:
UQCRFS1 is named in the same sentence as 47 diseases in open-access papers, as found by Europe PMC text mining. Sharing a sentence is not in itself a finding about the gene and the disease. The quoted sentences say what the papers report.
breast carcinoma (8 papers, 2011 to 2023). "The UQCRFS1 gene was overexpressed in gastric and breast cancer; gene amplification was identified as causative for upregulation in both tumors." (PMID 27845902, 2016). "For example, ubiquinol cytochrome c reductase (UQCRFS1) is amplified in a subset of breast cancers and is associated with higher tumor grade." (PMID 27136895, 2016). "Knockdown of UQCRFS1 in breast cancer cell lines reduced the mitochondrial membrane potential and impaired matrigel invasion." (PMID 27845902, 2016). "UQCRFS1 has been reported to be highly expressed in gastric and breast cancer, but the mechanism remains unclear." (PMID 37221238, 2023). "UQCRFS1, COX5B, and NDUFB8 expression was blunted by both SIRT6 silencing in MDA-MB-231 cells and by the Sirt6 heterozygous deletion in mouse mammary tumors." (PMID 33482921, 2021). "Taken together, our results suggest that UQCRFS1, POP4, C19ORF12, CCNE1 and C19ORF2 are overexpressed in primary breast cancers and/or breast cancer cell lines harbouring their amplification, and may constitute potential drivers of this amplicon." (PMID 22433433, 2012).
ovarian carcinoma (5 papers, 2011 to 2023). A malignant neoplasm originating from the surface ovarian epithelium. "We found that UQCRFS1 was highly expressed in ovarian cancer and was associated with poor prognosis." (PMID 37221238, 2023). "We selected A2780 and OVCAR8 cells with relatively high expression of UQCRFS1 from four ovarian cancer cell lines, and western blot analysis showed that UQCRFS1 was stably knocked down." (PMID 37221238, 2023). "The query of this gene in cBioPortal indicated that UQCRFS1 is either amplified or overexpressed in 26% of ovarian cancer patients." (PMID 34439877, 2021). "Increased expression of UQCRFS1 correlated with the reduced overall survival of ovarian cancer patients." (PMID 34439877, 2021). "Increased amplification or expression seen with UQCRFS1 in ovarian cancer patients, prompted us to carry out in silico analysis of its expression profile and overall survival rate of the ovarian cancer patients who show the altered expression of UQCRFS1." (PMID 34439877, 2021). "Consequently, the purposes of the current study were to determine the expression pattern and prognostic value of UQCRFS1 in ovarian cancer and explore the possible mechanisms affecting the development of ovarian cancer." (PMID 37221238, 2023). "High expression of UQCRFS1 indicates a poor ovarian cancer prognosis." (PMID 37221238, 2023). "Subsequently, the expression of the UQCRFS1 gene in four ovarian cancer cell lines was detected." (PMID 37221238, 2023). "More strikingly, the cBioPortal analysis indicates further that the aberrant expression of UQCRFS1 could be correlated with the reduced overall survival of ovarian cancer patients." (PMID 34439877, 2021). "Considering the late-stage expression profile of GNAi2/gip2 in ovarian cancer, the hub and bottleneck nodes identified here, especially the metabolic signaling nodes such as UQCRFS1, should provide newer targets for the development of second-line targeted therapy for advanced ovarian cancers." (PMID 34439877, 2021). "We hypothesized that UQCRFS1 is related to the occurrence and development of ovarian cancer." (PMID 37221238, 2023). "Oncoprint profile of CYCS, VEGFA, IL6, UQCRC1, UQCRFS1, COX5B, ACKR3/CXCR7, and FYN indicated that these genes were either amplified or overexpressed in 4–25% of the ovarian cancer patients." (PMID 34439877, 2021). "Consistent with our study showing overexpression of RISP in breast tumors and other tumors, previous studies report genetic amplification of the UQCRFS1/RISP gene not only in breast but also in ovarian cancers and in leukemia." (PMID 21901141, 2011). "The identification of CYCS, VEGFA, IL6, UQCRC1, UQCRFS1, COX5B, ACKR3/CXCR7, and FYN as pro-tumorigenic nodes designates them as the novel and potentially druggable targets for effective targeted adjuvant therapy for ovarian cancer." (PMID 34439877, 2021). "The prognosis and biological functions of UQCRFS1 in ovarian cancer (OC) have not been evaluated." (PMID 37221238, 2023).
gastric cancer (4 papers, 2017 to 2025). A primary or metastatic malignant neoplasm involving the stomach. "The impairment of UQCRFS1, involved in mitochondrial stability, electron transport driving oxidative phosphorylation, expression was described in gastric cancers where it is frequently amplified and associated to tumor progression." (PMID 34320944, 2021). "UQCRFS1 has been clarified to play an important role in mitochondrial diseases and a variety of cancers, including ovarian tumor, gastric cancer, and Cutaneous Melanoma." (PMID 40524231, 2025). "Another identified gene target UQCRFS1 appears to be involved in the progression of gastric cancers and in the development of more aggressive phenotype of breast cancer." (PMID 33420254, 2021).
glioma (2 papers, 2022). A benign or malignant brain and spinal cord tumor that arises from glial cells (astrocytes, oligodendrocytes, ependymal cells). "Most cellular metabolism genes investigated in glioma cell lines (ATP5A1, COX5A, CPT2, PFKL, and UQCRFS1) were found to be statistically downregulated." (PMID 36142793, 2022).
GRACILE syndrome (2 papers, 2023 to 2025). GRACILE syndrome is an inherited lethal mitochondrial disorder characterized by fetal growth restriction (GR), aminoaciduria (A), cholestasis (C), iron overload (I), lactacidosis (L), and early death (E). "In the GRACILE syndrome, the incorporation of Rieske iron-sulfur protein (RISP/UQCRFS1) into the mitochondrial respiratory chain complex III is decreased due to the BCS1L mutation, but the magnitude is highly tissue-specific." (PMID 41149808, 2025). "Our study showed that kidney organoids represent a promising tissue model for the study of the GRACILE syndrome, as the molecular Rieske iron-sulfur protein (RISP/UQCRFS1) phenotype of the disease was replicated in iPSC-derived kidney cells, in a cell-autonomous manner." (PMID 41149808, 2025).
acute lymphoblastic leukemia (1 paper, 2016). Leukemia with an acute onset, characterized by the presence of lymphoblasts in the bone marrow and the peripheral blood. "Similarly, UQCRFS1 was methylated in acute lymphoblastic leukemia cells." (PMID 27845902, 2016).
breast tumor (1 paper, 2011). "UQCRFS1/RISP knockdown in breast tumor cell line led to decreased mitochondrial membrane potential as well as a decrease in matrigel invasion." (PMID 21901141, 2011). "Determination of Complex III subunit gene expression identified over expression and co-regulation of UQCRFS1 (encoding RISP protein) and UQCRH (encoding Hinge protein) in 6 out of 9 human breast tumors." (PMID 21901141, 2011). "Analyses of UQCRFS1/RISP expression in additional matched normal and breast tumors demonstrated an over expression in 14 out of 40 (35%) breast tumors." (PMID 21901141, 2011). "In all 5 cases, UQCRFS1 (RISP protein) gene expression was higher in the breast tumor when compared to its normal breast tissue counterpart." (PMID 21901141, 2011). "A total of 8 out of 9 breast tumors show coordinate regulation of UQCRFS1 and UQCRH suggesting a common factor involved in transcriptional regulation of these two genes." (PMID 21901141, 2011).
cerebral toxoplasmosis (1 paper, 2021). Infections of the brain caused by the protozoan toxoplasma gondii that primarily arise in individuals with immunologic deficiency syndromes (see also aids-related opportunistic infections). "However, biological roles of Vamp2 along with Uqcrfs1 and Pkm in cerebral toxoplasmosis still need further exploration." (PMID 34367142, 2021).
clear cell renal carcinoma (1 paper, 2021). A malignant epithelial neoplasm of the kidney characterized by the presence of lipid-containing clear cells within a vascular network. "Opposite results are shown in clear cell renal carcinoma; UQCRFS1 is downregulated, probably due to a DNA hypermethylation of that region." (PMID 34320944, 2021).
iron deficiency (1 paper, 2020). "Conversely, in TTP KO mouse hearts, UQCRFS1 levels were not decreased in iron deficiency, resulting in abnormalities of Fe/S cluster function, oxidative damage, and cardiac dysfunction in the setting of iron deficiency." (PMID 33569048, 2020).
Optic neuropathy (1 paper, 2017). "Human mutations in UQCRFS1, the human ortholog of isp-1, the Complex III Rieske iron-sulfur protein, have not been directly associated with human disease, but Complex III deficiency in general is linked to optic neuropathy." (PMID 28539870, 2017).
prion disease (1 paper, 2023). A transmissible disease that is caused by a protein that is able to induce abnormal folding of normal cellular proteins, leading to characteristic spongiform brain changes, which are associated with neuronal loss without an inflammatory response. "The genes predicted to be regulated in the “Prion disease” pathway by heroin-associated miRNAs included several transcription factors that have been demonstrated to regulate expression of proteins observed in our heroin-associated protein list, including Atp5pd (Elk1) and Uqcrfs1 (Elk1)." (PMID 38389822, 2023).
tuberculous pleurisy (1 paper, 2021). "A total of eight possible biomarkers of tuberculous pleurisy were screened (RPL17, UBA7, NDUFB8, UQCRFS1, JUNB, PSMC4, PHPT1, and MAPK11)." (PMID 34925441, 2021).
tumor (11 papers, 2011 to 2025). "However, the underlying mechanism of UQCRFS1 in tumor progression and immunotherapy resistance should be further investigated in the future research, which will enhance the utilization of UQCRFS1 in clinical practices." (PMID 40524231, 2025). "Among the MCI-included malignant genes, UQCRFS1 has been documented to possess the vital involvement in tumor progression." (PMID 40524231, 2025). "Ultimately, UQCRFS1 knockdown dampened the proliferative and migratory competence in vitro as well as tumor growth in vivo of TNBC cells." (PMID 40524231, 2025). "The identification of hub genes like GRSF1 and UQCRFS1 and their link to favorable metabolic profiles offers novel insights into tumor neovascularization and metastasis, with significant clinical implications for targeting metabolic pathways in CRC therapy." (PMID 38947396, 2024). "To further explore the function of UQCRFS1, we did a correlation analysis between the UQCRFS1 gene and the tumour-related dataset." (PMID 37221238, 2023). "Western blotting and IHC results also demonstrated that UQCRFS1 high-expression in OC tumour tissues compared with normal tissues, which has the potential to predict the prognosis of patients." (PMID 37221238, 2023). "Furthermore, our results indicate that UQCRFS1 affects tumour cell proliferation, cell cycle, apoptosis, and DNA damage, which may be related to the AKT/mTOR signalling pathway." (PMID 37221238, 2023). "Thus, UQCRC1 and UQCRFS1 seem to be involved in carcinogenesis, but deregulation may be depending upon the tumor entity, and its expression is decreased in ccRCC." (PMID 27845902, 2016). "We also find that we are able to successfully transfer our cancer models to tumour-adjacent tissue when inspecting the top 6 genes explained by CNVs (i.e. LLPH, YEATS4, UQCRFS1, POP4, CNOT2, and CAND1)." (PMID 40041206, 2025). "Ultimately, UQCRFS1, one of crucial genes in MCI model, was deciphered to be a deleterious factor in tumor progression and a potential target in TNBC treatment." (PMID 40524231, 2025). "In tumor 9ebac79d-8b38-4469-837e-b834725fe6d5, the translocation was predicted to lead to a neo-TAD resulting from merging the TADs of TOB1-AS1 and UQCRFS1." (PMID 39051548, 2024). "Therefore, UQCRFS1 high-expression might play a tumour-promoting role." (PMID 37221238, 2023). "The largest number of changes in gene expression (n = 8) between tumour and non-malignant groups were identified in metabolic genes (PFKL, ATP5A1, UQCRFS1, CPT2, COX5A, ACLY, GPD2, and G6PD)." (PMID 36142793, 2022).
cancer (8 papers, 2011 to 2025). A tumor composed of atypical neoplastic, often pleomorphic cells that invade other tissues. "We determined if expression of UQCRFS1 (encoding RISP protein) and UQCRH (encoding Hinge) was also increased in other cancers." (PMID 21901141, 2011). "However, at least, we show that UQCRFS1 is highly expressed in OC, thus providing more energy for cancer development, which may make UQCRFS1 a potential target for OC therapy." (PMID 37221238, 2023). "Analyzing gene expression and DNA methylation in The Cancer Genome Atlas cohort revealed an inverse correlation of gene expression and DNA methylation, suggesting that DNA hypermethylation is regulating the expression of UQCRC1 and UQCRFS1." (PMID 27845902, 2016).
blood disorders (1 paper, 2025). "Furthermore, four genes–UQCRFS1, PTPN6, RALY and ZMYM4–were identified for their associations with traits such as aging, forebrain and nervous system morphology, lung and bone morphology, neurodegenerative diseases and blood disorders." (PMID 40656995, 2025).
UQCRFS1 also shares sentences with these, for which no sentence is quoted: infection (4 papers); osteosarcoma (3); Parkinson disease (3); Alzheimer disease (2); Depression (2); mitochondrial disease (2); pulmonary hypertension (2); triple-negative breast carcinoma (2); alopecia totalis (1); Aminoaciduria (1); anemia (1); asthma (1); Bjornstad syndrome (1); cholestasis (1); cutaneous melanoma (1); hepatopathy (1); HIV-1 infection (1); Huntington disease (1); hypertrichosis (1); ischemia (1); lactic acidosis (1); leukemia (1); listeriosis (1); liver disorder (1); Mitochondrial encephalopathy (1); neurodegenerative disease (1); oncocytoma (1); ovarian tumor (1); Pancytopenia (1); steatosis (1).
A further 1 disease shares a sentence with UQCRFS1 in 1 paper.